RNY3P14 (RNY3 pseudogene 14)
Gene: Miscellaneous RNA gene on chromosome 8 (70,357,347 to 70,357,448, forward strand). Ensembl gene ENSG00000207036.
Homologues: Orthologues: chimpanzee Y_RNA (99% identical), macaque Y_RNA (98% identical). Paralogues in human: Y_RNA (91% identical), RNY3 (90% identical), Y_RNA (90% identical), Y_RNA (89% identical), RNY3P1 (88% identical), Y_RNA (88% identical), Y_RNA (87% identical), Y_RNA (86% identical), RNY3P16 (85% identical), Y_RNA (85% identical), RNY3P11 (84% identical), Y_RNA (84% identical), and 94 more.